SMARCAL1 (SNF2 related chromatin remodeling annealing helicase 1)
Description:
ATP-dependent annealing helicase that binds selectively to fork DNA relative to ssDNA or dsDNA and catalyzes the rewinding of the stably unwound DNA. Rewinds single-stranded DNA bubbles that are stably bound by replication protein A (RPA). Acts throughout the genome to reanneal stably unwound DNA, performing the opposite reaction of many enzymes, such as helicases and polymerases, that unwind DNA. May play an important role in DNA damage response by acting at stalled replication forks.
Synonyms: hHARP; HARP
Tractability: PROTAC: ubiquitination databases record sites on it; its protein half-life has been measured.
Gene: Protein-coding gene on chromosome 2 (216,412,383 to 216,483,056, forward strand). Ensembl gene ENSG00000138375.
Subcellular location: Nucleus
Subcellular location (Human Protein Atlas): Nucleoplasm
Gene Ontology:
Molecular function: ATP hydrolysis activity; ATP-dependent DNA/DNA annealing activity; protein binding; ATP binding; ATP-dependent activity, acting on DNA
Biological process: DNA damage response; double-strand break repair via nonhomologous end joining; regulation of transcription by RNA polymerase II; replication fork processing; DNA repair; t-circle formation
Cellular component: DNA replication factor A complex; nucleoplasm; nucleus; site of double-strand break; nuclear replication fork
Genetic constraint (gnomAD): Loss-of-function variants: 57 observed, 89.4 expected, observed/expected ratio (o/e) 0.64, 90% interval 0.51 to 0.8. The upper end of that interval is the gene's LOEUF score, 0.8, which puts it in group 3 of 6, group 1 being the genes least tolerant of losing a copy. Missense variants: 1,038 observed, 1,207.5 expected, observed/expected ratio (o/e) 0.86, 90% interval 0.82 to 0.9. Synonymous variants: 418 observed, 469.53 expected, observed/expected ratio (o/e) 0.89, 90% interval 0.82 to 0.96.
Gene-disease validity (ClinGen):
ClinGen rates the evidence that SMARCAL1 causes each of these diseases.
Schimke immuno-osseous dysplasia (autosomal recessive): Definitive. A multisystem disorder characterized by spondyloepiphyseal dysplasia and disproportionate short stature, facial dysmorphism, T-cell immunodeficiency, and glomerulonephritis with nephrotic syndrome.
Homologues: Orthologues: chimpanzee SMARCAL1 (99% identical), macaque SMARCAL1 (97% identical), rabbit SMARCAL1 (82% identical), dog SMARCAL1 (80% identical), pig SMARCAL1 (79% identical), guinea pig SMARCAL1 (78% identical), rat Smarcal1 (74% identical), mouse Smarcal1 (71% identical), tropical clawed frog smarcal1 (53% identical), zebrafish smarcal1 (18% identical). Paralogues in human: ZRANB3 (23% identical), CHD7 (18% identical), SMARCA2 (18% identical), BTAF1 (18% identical), SMARCA4 (18% identical), CHD3 (17% identical), CHD5 (17% identical), CHD8 (17% identical), CHD4 (16% identical), CHD9 (16% identical), ATRX (16% identical), EP400 (16% identical), and 18 more.
Diseases named in the same sentence as SMARCAL1 in open-access papers:
SMARCAL1 is named in the same sentence as 73 diseases in open-access papers, as found by Europe PMC text mining. Sharing a sentence is not in itself a finding about the gene and the disease. The quoted sentences say what the papers report.
Schimke immuno-osseous dysplasia (24 papers, 2009 to 2025). "Schimke immuno-osseous-dysplasia (SIOD) is an autosomal recessive multi-system disease due to pathogenic variants in SMARCAL1, a gene involved in chromatin remodeling." (PMID 39292251, 2025). "Biallelic mutations of the chromatin regulator SMARCAL1 cause Schimke Immunoosseous Dysplasia (SIOD), characterized by severe growth defects and premature mortality." (PMID 38129665, 2023). "Mutations in SMARCAL1 cause Schimke Immuno-osseous Dysplasia (SIOD) while mutations in BRG1 are associated with Coffin-Siris Syndrome (CSS4)." (PMID 35784471, 2022). "Mutations in SMARCAL1 cause Schimke Immuno-osseous Dysplasia (SIOD), an autosomal recessive disorder characterized by renal dysfunction, spondyloepiphyseal dysplasia, and T-cell immunodeficiency." (PMID 35784471, 2022). "Mutations in SMARCAL1 lead to Schimke immuno-osseous dysplasia (SIOD), while HLTF/ZRANB3-deficient cells are vulnerable to replication stress and contribute to tumorigenesis." (PMID 34041245, 2021). "Mutations in the SMARCAL1 gene cause a rare autosomal recessive disease, Schimke immuno-osseous dysplasia (SIOD), which is characterized by short stature, kidney disease and a severely compromised immune system." (PMID 26089390, 2015). "Schimke immuno-osseous dysplasia (SIOD) is an autosomal recessive inherited disease in which the SMARCAL1 gene is mutated on chromosome 2; SIOD is mainly characterized by spondyloepiphyseal dysplasia, lymphopenia with defective cellular immunity, and progressive renal dysfunction." (PMID 32393263, 2020). "SMARCAL1 mutations cause Schimke Immunoosseous Dysplasia (SIOD)." (PMID 23671665, 2013). "Schimke immuno-osseous dysplasia (SIOD) is a very rare disease with a prevalence of 1:1–3,000,000, caused by the autosomal recessive mutations in the SMARCAL1 gene, coding for a protein responsible for chromatin remodeling and DNA repair." (PMID 39153074, 2024). "Mutations in Smarcal1 also cause severe skeletal disorders, such as Schimke immuno-osseous dysplasia (SIOD), characterized by growth defects, immune deficiencies and other complex appearance." (PMID 38164361, 2024). "Moreover, the metabolism of the R-loop is also linked to the pathogenesis of “replication-related” genetic diseases, such as Schimke Immuno-osseous dysplasia, which is caused by mutations in SMARCAL1 or XPF-ERCC1-related syndrome, which has been linked to chronic inflammation." (PMID 35163467, 2022). "Schimke Immuno-osseous Dysplasia (SIOD) is a rare autosomal recessive disease caused by a biallelic mutation in SMARCAL1 gene." (PMID 30026777, 2018). "Schimke immuno-osseous dysplasia (SIOD) caused by mutations in SMARCAL1 is an ultra-rare disease characterized by specific facial features, skeletal dysplasia, and steroid-resistant nephrotic syndrome, which often leads to kidney failure and requires transplantation." (PMID 36330520, 2022). "Mutations in SMARCAL1 (SWI/SNF-related, matrix-associated, actindependent regulator of chromatin, subfamily a-like 1) are involved in the development of Schimke immunoosseous dysplasia (SIOD)." (PMID 22693670, 2012). "Mutations in SMARCAL1 (SWI/SNF-related, matrix-associated, actin-dependent regulator of chromatin, subfamily A-like 1) cause Schimke immuno-osseous dysplasia (SIOD; OMIM 242900)." (PMID 19721813, 2009). "Schimke Immuno-Osseous Dysplasia (SIOD) is an autosomal recessive multi-system disorder, with the genetic cause of biallelic loss-of-function mutation in SMARCAL1 (SWI/SNF-related, matrix-associated, actin-dependent regulator of chromatin, subfamily a-like 1) gene." (PMID 38198013, 2024). "Arteriosclerosis and emphysema develop in individuals with Schimke immuno-osseous dysplasia (SIOD), a multisystem disorder caused by biallelic mutations in SMARCAL1 (SWI/SNF-related, matrix-associated, actin-dependent regulator of chromatin, subfamily a-like 1)." (PMID 22998683, 2012).
Schimke immuno-osseous dysplasia (continued). "Schimke immuno-osseous dysplasia (SIOD) is a multisystemic disorder caused by biallelic mutations in the SWI/SNF-related matrix-associated actin-dependent regulator of chromatin, subfamily A-like 1 (SMARCAL1) gene." (PMID 27816064, 2016). "SMARCAL1/HARP is an annealing helicase that functions in the repair and restart of damaged DNA replication forks and has been linked to AR Schimke immuno-osseous dysplasia (SIOD), which can cause T-cell immunodeficiency, but is also accompanied by short stature and other phenotypes." (PMID 35967429, 2022).
renal failure (7 papers, 2011 to 2025). "SIOD, which is caused by mutations of SMARCAL1, is a rare autosomal recessive disease with its prominent features being skeletal dysplasia, T cell deficiency, and renal failure." (PMID 21914180, 2011). "We speculate that the more aggressive course of renal failure in patients with SMARCAL1-associated disease relative to podocin deficiency—which exclusively affects the podocyte—may be related to additional functional effects of defective SMARCAL1 expressed in other nephron structures." (PMID 28796785, 2017). "Before kidney transplantation, patients receive immunosuppressive therapy, which can delay, but not fully prevent, kidney failure, probably due to the important roles of SMARCAL1 in kidney development." (PMID 36330520, 2022).
glioma (6 papers, 2018 to 2026). A benign or malignant brain and spinal cord tumor that arises from glial cells (astrocytes, oligodendrocytes, ependymal cells). "SMARCAL1 localizes to ALT-associated PML (Promyelocytic leukemia protein) bodies in ALT-positive glioma cell lines, including IDH-mutant astrocytomas." (PMID 41520142, 2026). "Higher scores of stromal and immune cells were associated with elevated SMARCAL1 expression in Glioma and KIRC tissues, indicating a strong positive correlation with the ESTIMATE score." (PMID 39994264, 2025). "In summary, SMARCAL1 expression holds diagnostic and prognostic significance across various cancers, including Glioma." (PMID 39994264, 2025). "Tumor Mutational Burden (TMB) levels and SMARCAL1 expression in Glioma, LUAD, and KIRC were found to be positively correlated." (PMID 39994264, 2025). "Variations in SMARCAL1 expression levels among Glioma patients were found to be linked with distinctive clinical and pathological characteristics." (PMID 39994264, 2025). "In the SMARCAL1 high/low expression cohorts, thirty altered genes were found in the mutation spectrum in Glioma, LUAD, LIHC, KIRC, and UCEC." (PMID 39994264, 2025). "Elevated SMARCAL1 is linked to poor outcomes in Glioma, LUAD, and LIHC but correlates with better survival in KIRC." (PMID 39994264, 2025). "Subsequently, the diagnostic performance of SMARCAL1 in Glioma, LUAD, LIHC, KIRC, and UCEC were assessed using ROC curves." (PMID 39994264, 2025). "Particularly noteworthy, within the TCGA database, SMARCAL1 expression exhibited significant increases in higher-grade Gliomas and IDH-wildtype Gliomas, as well as in samples lacking 1p/19q codeletion." (PMID 39994264, 2025). "Our findings indicate that SMARCAL1 is overexpressed in several cancers, such as Glioma, LUAD, KIRC, and LIHC, impacting prognosis." (PMID 39994264, 2025). "In summary, our findings indicate that Gliomas characterized by higher malignancy levels tend to exhibit enriched SMARCAL1 expression." (PMID 39994264, 2025). "Results indicated elevated expression levels of SMARCAL1 in Glioma tissues compared to normal tissues, with the protein primarily located within the nucleus." (PMID 39994264, 2025). "According to the findings of the Cox assessment, SMARCAL1 is identified as an adverse predictor of overall survival (OS) in Glioma, LUAD, and LIHC (P < 0.05), but exhibits potential as a beneficial factor in KIRC (P < 0.05)." (PMID 39994264, 2025). "Additionally, we used mRNA sequencing data from the CGGA and TCGA databases to investigate the expression levels of SMARCAL1 in various pathological subtypes of Glioma." (PMID 39994264, 2025). "According to our findings, SMARCAL1 is more abundant in malignant Glioma subtypes, which may indicate that it might be used as a prognostic indicator to estimate the risk of developing cancer." (PMID 39994264, 2025). "Therefore, we investigated the correlation between SMARCAL1 expression and immune infiltration in Glioma, LUAD, LIHC, KIRC, and UCEC." (PMID 39994264, 2025). "Our analysis of previous sequencing studies reveals that among diffuse gliomas, SMARCAL1 mutations appear to be absent in lower-grade gliomas (WHO grade II–III) and only present in GBMs." (PMID 29802247, 2018). "In Glioma, LUAD, LIHC, KIRC, and UCEC, SMARCAL1 expression exhibited significant correlations with forty-two, thirty-two, twenty-four, fifty, and eighty-three drugs, respectively (|R|> 0.3, p < 0.05)." (PMID 39994264, 2025). "We first analyzed the expression levels of SMARCAL1 and CD276 in glioma cell lines (U118-MG, U87-MG, A172) and the normal human astrocyte (NHA) cell line." (PMID 39994264, 2025). "At the protein level, both SMARCAL1 and CD276 were also more highly expressed in glioma cell lines than in NHA." (PMID 39994264, 2025).
glioma (continued). "The results of our investigation showed a strong relationship between the expression of SMARCAL1 and several immune checkpoint genes, including CD276, NRP1, TNFSF4, CD40, CD200, and CD80 in Glioma, LUAD, LIHC, KIRC, and UCEC." (PMID 39994264, 2025).
Immunodeficiency (6 papers, 2011 to 2025). Failure of the immune system to protect the body adequately from infection, due to the absence or insufficiency of some component process or substance. "The mutation in the SMARCAL1 gene, which is essential for DNA stabilization, contributes to immunodeficiency and heightened susceptibility to infections and autoimmune diseases, likely due to disturbances in T cell regulation." (PMID 41368056, 2025). "As for the immunodeficiency, however, it likely arises from a dysfunction of SMARCAL1, the enzyme mutated in SIOD, within the lymphocytic lineages." (PMID 21914180, 2011). "Our patient, carrying a novel SMARCAL1 mutation and presenting with juvenile-onset disease, progressed to ESKD but had only mild immune dysfunction, making kidney transplantation a potential treatment option." (PMID 41953243, 2025). "Consistent with such a cell autonomous model, SMARCAL1 is highly expressed in the bone marrow lineages, and the limited data on one SIOD patient suggests that bone marrow transplantation can ameliorate the immunodeficiency." (PMID 21914180, 2011).
glioblastoma (5 papers, 2018 to 2025). The most malignant astrocytic tumor (WHO grade IV). "D06MG, a glioblastoma cell line with SMARCAL1 nonsense mutation and intact ATRX, was ALT+ as measured by APBs and C-circles." (PMID 34069193, 2021). "Here we report the genetic landscape of TERTpWT-IDHWT glioblastoma and identify SMARCAL1 inactivating mutations as a novel genetic mechanism of ALT." (PMID 29802247, 2018). "A recent study reported the genetic landscape of TERTpWT-IDHWT glioblastomas and identified the occurrence of SMARCAL1 inactivating mutations as a novel mechanism of alternative lengthening of telomeres ALT." (PMID 30279357, 2018). "Secondly, in WT hTERT and IDH glioblastoma, all ALT+ tumors have either ATRX loss or SMARCAL1 mutation." (PMID 34069193, 2021). "SMARCAL1 knockout in ALT− glioblastoma cells, U87MG and U251MG, significantly increased C-circles and APBs." (PMID 34069193, 2021). "A study in ALT positive glioblastoma found that SMARCAL1 mutations, like those of ATRX and DAXX, correlate well with ALT status, with over half of ALT positive glioblastoma samples harboring SMARCAL1 mutations." (PMID 32039009, 2019). "Here, the authors present a genetic landscape of TERTpWT-IDHWT glioblastoma, identifying a telomerase-positive subgroup driven by TERT-structural rearrangements and an ALT-positive subgroup with mutations in ATRX or SMARCAL1." (PMID 29802247, 2018). "Similar hypotheses can be also drawn for SMARCAL1 (which is often lost in ALT glioblastomas and is mutually exclusive with ATRX)." (PMID 40725011, 2025).
Fanconi anaemia (4 papers, 2019 to 2025). "This indicates that the DNA-remodelling motor function of FANCM is required in SMARCAL1-deficient cells, but its recruitment of the Fanconi anaemia and BLM–TOP3A–RMI complexes is dispensable." (PMID 40205037, 2025). "From this point of view, SMARCAL1-depleted iPSCs behave more like those generated from FA-A cells, which are derived from patients with Fanconi anaemia and retain all the key cellular defects of the syndrome." (PMID 31515241, 2019). "We observed no genetic interaction between SMARCAL1 and Fanconi anaemia genes involved in ICL repair and homologous recombination, such as FANCD2 or FANCA." (PMID 40205037, 2025). "Surprisingly, guides targeting the fork reversal factors (SMARCAL1, HLTF, ZRANB3, SHPRH) or components of the Fanconi Anaemia pathway were neither enriched nor depleted, despite previous studies suggesting a genetic interaction between some of these factors and PRIMPOL in transformed cell lines." (PMID 37971291, 2024).
immuno-osseous dysplasia (4 papers, 2022 to 2025). "Schimke immuno-osseous dysplasia is a rare multisystemic disorder caused by biallelic loss of function of the SMARCAL1 gene that plays a pivotal role in replication fork stabilization and thus DNA repair." (PMID 39153074, 2024). "A homozygous missense variant of the SMARCAL1 gene was described in two siblings with Schimke immuno-osseous dysplasia, one of whom developed a classical type of congenital mesoblastic nephroma combined with disturbed immunoglobulin production and profound lymphopenia as well." (PMID 40282457, 2025).
focal segmental glomerulosclerosis (3 papers, 2016 to 2025). A renal disorder characterized by sclerotic lesions in the glomeruli. "Changes in gene expression underlie the arteriosclerosis and T-cell immunodeficiency of SIOD; therefore, we hypothesized that SMARCAL1 deficiency causes the focal segmental glomerulosclerosis (FSGS) of SIOD by altering renal gene expression." (PMID 27816064, 2016).
hyperlipidemia (3 papers, 2012 to 2025). "The discovery of SmarcAL1’s involvement in regulating cellular lipid metabolism aligns with the hyperlipidemia observed in SIOD patients." (PMID 38129665, 2023).
osteosarcoma (3 papers, 2019 to 2023). A usually aggressive malignant bone-forming mesenchymal neoplasm, predominantly affecting adolescents and young adults. "Germline P/LP variants in SMARCAL1, another gene related to the DNA damage pathway, was detected in three patients with osteosarcoma." (PMID 32371905, 2020). "In additional, several other non-DNA binding transcriptional regulators are present among all Supertargets: a component of the cohesion complex STAG1 (Ewing sarcoma), SMARCA2 (lung) and SMARCAL1 (osteosarcoma)." (PMID 37297004, 2023). "In osteosarcoma, SMARCAL1, IRS1, SUB1, HMGA2, and FANCM were identified as Supertargets." (PMID 37297004, 2023). "To confirm this result, we analyzed the seven osteosarcoma tumor samples for ATRX, DAXX, SMARCAL1, H3.3, and SLX4IP protein expression by immunoblotting." (PMID 31447390, 2019).
astrocytomas (2 papers, 2021 to 2026). "Furthermore, sequencing of three subependymal giant cell astrocytoma (SEGA)-like astrocytomas in NF1 mutant patients with ALT and intact ATRX have revealed genetic alterations in RECQL4, Fanconi anemia complementation group genes (FANCD2, FANCF, and FANCG), and SMARCAL1." (PMID 34069193, 2021).
breast carcinoma (2 papers, 2022 to 2025). "SMARCAL1-deficient breast cancer cell lines could enhance the response to immunotherapy." (PMID 41531533, 2025). "Indeed, one such molecule, Active DNA-dependent ATPase A inhibitor (ADAADi) targets the ATPase domain of both SMARCAL1 and BRG1 and has been shown to be effective against breast cancer cells lines as well as prostate tumors developed in mouse models." (PMID 35784471, 2022).
lymphopenia (2 papers, 2022 to 2025). Reduction in the number of lymphocytes. "We have shown that a lethal homozygous SMARCAL1 mutation causing severe kidney disease and lymphopenia in a boy did not impair TCR signaling in a T-cell model derived from the patient." (PMID 36330520, 2022).
renal dysfunction (2 papers, 2013 to 2015). "For example, following the array study, case 012 was diagnosed with Schimke immune-osseous dysplasia, an autosomal-recessive pleiotropic disorder caused by loss of function mutations in SMARCAL1 leading to spondyloepiphyseal dysplasia, renal dysfunction and T-cell immunodeficiency." (PMID 24053112, 2013). "As symptoms of SIOD include renal dysfunction and cereberal ischemia, we hypothesized that SMARCAL1 expression during differentiation is critical for repressing c-myc expression." (PMID 26648259, 2015).